UBE2T (ubiquitin conjugating enzyme E2 T)
Diseases named in the same sentence as UBE2T in open-access papers (continued):
Sharing a sentence is not in itself a finding about the gene and the disease.
cervical cancer (continued). "However, overexpression of UBE2T contributed to cervical cancer cell growth and metastasis." (PMID 34703898, 2021). "However, the oncogenic role of UBE2T in cervical cancer remains unclear." (PMID 34703898, 2021). "Silencing of UBE2T downregulated protein expression of SOX2, Oct-4, and Nanog in cervical cancer cells reduced self-renewal capacity." (PMID 34703898, 2021). "Therefore, UBE2T might be a novel target for the treatment of cervical cancer." (PMID 34703898, 2021). "Furthermore, ectopic UBE2T expression promoted protein expression of glucose-regulated protein 78 (GRP78) and focal adhesion kinase (FAK) phosphorylation in cervical cancer cells." (PMID 34703898, 2021). "However, the role of UBE2T in cervical cancer is still not clear." (PMID 34703898, 2021).
colorectal cancer (3 papers, 2021 to 2026). A primary or metastatic malignant neoplasm that affects the colon or rectum. "UBE2T overexpression facilitates the growth, proliferation, and invasion of colorectal cancer cells and suppresses apoptosis." (PMID 33934686, 2021).
malignant melanoma (3 papers, 2022 to 2024). "Ubiquitin-conjugating enzyme E2 T (UBE2T) mRNA was significantly highly expressed in malignant melanoma tissues, associated with the poor overall survival rate of malignant melanoma patients." (PMID 38795139, 2024). "For instance, in malignant melanoma, UBE2T overexpression significantly promotes the proliferation, invasion, and migration of malignant melanoma cells but inhibits apoptosis." (PMID 39791716, 2024). "In malignant melanoma, miR-498 inhibits progression by targeting UBE2T, while in clear cell renal cell carcinoma (ccRCC), miR-182-5p suppresses UBE2T protein expression, thereby inhibiting cell proliferation, migration, and invasion by targeting UBE2T mRNA." (PMID 39791716, 2024).
cardiomyopathy (2 papers, 2020 to 2021). A disease of the heart muscle or myocardium proper. "The team discovered that the CaMKII-δ9 isoform may mediate cardiomyopathy by causing cardiomyocyte DNA damage and cell death due to disrupted UBE2T (Ubiquitin-conjugating enzyme E2 T)-mediated DNA repair." (PMID 34575212, 2021).
chordoma (2 papers, 2021 to 2022). Chordomas are rare malignant tumors arising from embryonic remnants of the notochord in axial skeleton. "In conclusion, DEPDC1B regulates the progression of human chordoma through UBE2T-mediated ubiquitination of BIRC5, suggesting that it may be a promising candidate target with potential therapeutic value." (PMID 34330893, 2021). "Therefore, the significant breakthrough that DEPDC1B regulates the progression of human chordoma through UBE2T-mediated ubiquitination of BIRC5 may provide a valuable target for molecular therapy of chordoma patients." (PMID 34330893, 2021). "DEPDC1B regulates the progression of human chordoma through UBE2T-mediated ubiquitination of BIRC5, which may be a promising candidate target in molecular therapy of chordoma patients." (PMID 34330893, 2021).
endometrial cancer (2 papers, 2024 to 2025). Primary or metastatic malignant neoplasm involving the endometrium (mucous membrane that lines the endometrial cavity). "UBE2T holds potential as a prospective indicator for diagnosing and predicting prognosis in endometrial cancer patients." (PMID 39367897, 2025). "Using data from The Cancer Genome Atlas (TCGA), Gene Expression Omnibus (GEO), and UALCAN databases, we analyzed the differential expression of UBE2T mRNA and protein in endometrial cancer (UCEC), along with its clinical relevance." (PMID 39367897, 2025). "Therefore, UBE2T expression levels can effectively predict the prognosis of endometrial cancer patients." (PMID 39367897, 2025). "In endometrial cancer, increased UBE2T expression may inhibit antitumor immune responses and is implicated in tumorigenesis, metastasis, and invasion, correlating with poorer survival outcomes." (PMID 39791716, 2024). "Therefore, it is hypothesized that UBE2T might promote the occurrence and development of endometrial cancer through upregulating mitochondrial protein expression and enhancing mitochondrial function." (PMID 39367897, 2025). "In summary, increased expression of UBE2T in endometrial cancer tissues may suppress the anti-tumor immune response in UCEC patients, participating in various biological processes such as tumor initiation, metastasis, and invasion, and correlating with poorer survival rates." (PMID 39367897, 2025). "Additionally, among the genes closely associated with UBE2T expression, genes like DTL, NUF2, and MELK may also contribute to the progression of endometrial cancer." (PMID 39367897, 2025). "Thus, UBE2T may facilitate endometrial cancer development by upregulating mitochondrial protein expression." (PMID 39791716, 2024).
esophageal cancer (2 papers, 2021 to 2022). A primary or metastatic malignant neoplasm involving the esophagus. "We first compared the expression of UBE2T in esophageal cancer and normal tissues by mining the Oncomine database." (PMID 34257599, 2021). "We next used the TCGA database to validate the differential expression of UBE2T between esophageal cancers and normal tissues." (PMID 34257599, 2021). "Studies retrieved from the Oncomine database regarding the comparison of UBE2T between esophageal carcinoma and normal tissue." (PMID 34257599, 2021).
esophageal squamous cell carcinoma (2 papers, 2021 to 2024). Esophageal squamous cell carcinoma (ESCC) is a type of esophageal carcinoma (EC) that can affect any part of the esophagus, but is usually located in the upper or middle third.
Ewing sarcoma (2 papers, 2023 to 2024). A small round cell tumor that lacks morphologic, immunohistochemical, and electron microscopic evidence of neuroectodermal differentiation. "Besides, IHC was used to identify the expression of UBE2T protein in Ewing’s sarcoma and normal tissues." (PMID 36910645, 2023). "Furthermore, validation set and IHC findings displayed that the expression level of UBE2T was significantly higher in the sick tissues of Ewing’s sarcoma patients than the control group, and IHC analysis revealed that UBE2T was mostly expressed in the cytoplasm of Ewing’s sarcoma cells." (PMID 36910645, 2023).
head and neck squamous cell carcinoma (2 papers, 2022 to 2024). A squamous cell carcinoma that arises from any of the following anatomic sites: lip and oral cavity, nasal cavity, paranasal sinuses, pharynx, larynx, and salivary glands. "In head and neck squamous cell carcinoma (HNSC), UBE2T overexpression also promotes tumor growth by activating NF-κB signaling and inducing ferroptosis." (PMID 39791716, 2024).
liver cirrhosis (2 papers, 2024 to 2025). "In HCC, a four-gene combination involving KIF4A, UBE2T, CDCA3, and CDCA5 can track disease progression from chronic active hepatitis B (CAH-B) and liver cirrhosis (LC) to HCC." (PMID 41361459, 2025). "However, no study reported the role of UBE2T in chronic active hepatitis B and liver cirrhosis." (PMID 38890649, 2024).
non-small cell lung adenocarcinoma (2 papers, 2017 to 2020). Type of epithelial lung cancer arising from glandular origin. "Of note we did not identify a significant proportion of molecular alterations in those tumors except for non-small cell lung adenocarcinoma patients, where UBE2T was amplified in 7.4% of the tumors, and DTL in 6.5%." (PMID 29235520, 2017). "In non-small cell lung adenocarcinomas, UBE2T and DTL were also amplified in around 7% of cases and linked with disease recurrence after surgical resection." (PMID 29235520, 2017).
retinoblastoma (2 papers, 2024). A malignant tumor that originates in the nuclear layer of the retina. "In retinoblastoma, high UBE2T expression enhances Th2 cell immune infiltration by activating the STAT3 pathway, promoting tumor formation and progression; however, further investigation into the specific UBE2T proteins involved in this activation is warranted." (PMID 39791716, 2024).
triple-negative breast carcinoma (2 papers, 2021 to 2025). An invasive breast carcinoma which is negative for expression of estrogen receptor (ER), progesterone receptor (PR), and human epidermal growth factor receptor 2 (HER2). "For example, the UBE2T inhibitor M435-1279 has shown promising preclinical efficacy in triple-negative breast cancer, and compound NSC697923 has demonstrated activity against UBC13 in lymphoma." (PMID 41446875, 2025).
COVID-19 (1 paper, 2025). A disease caused by infection with severe acute respiratory syndrome coronavirus 2. "In influenza, UBE2S, USP53, and TIMM10 were observed in this category, while in COVID-19, UBE2T, UBE2C, DTL, MT-ND2, UCHL1, and UBA52 were implicated." (PMID 41020849, 2025).
gastric tumor (1 paper, 2017). "Suppression of UBE2T also inhibits gastric tumor invasion and metastasis via the WNT signal pathway by inhibiting WNT5A and WNT7B, which in turn promotes GSK3B expression, activates β-Catenin, and inhibits the key oncogene c-Myc." (PMID 28427240, 2017). "The number of samples with high UBE2T expression was also higher for gastric tumor samples than for para-carcinoma samples (P < 0.05)." (PMID 28427240, 2017). "UBE2T expression was obviously increased in gastric tumors compared to para-carcinoma tissues (A: 40 ×, B: 100 ×, C: 400 ×)." (PMID 28427240, 2017). "Together, these data indicated that UBE2T knockdown also attenuated gastric tumor formation and growth in vivo." (PMID 28427240, 2017). "In this study, we first examined UBE2T expression in gastric tumor and para-carcinoma tissues samples collected during surgical operations." (PMID 28427240, 2017). "In addition, the UBE2T knockdown-induced increase in CDH1 (E-Cadherin) also inhibits gastric tumor formation and growth." (PMID 28427240, 2017). "Given that increased UBE2T expression is associated with carcinogenesis, we next examined whether suppression of UBE2T could inhibit and attenuate proliferation, invasion, and metastatic abilities in gastric tumors." (PMID 28427240, 2017). "UBE2T expression was increased in gastric tumors compared with para-carcinoma tissues." (PMID 28427240, 2017).
intrahepatic cholangiocarcinoma (1 paper, 2024). A carcinoma that arises from the intrahepatic bile duct epithelium in any site of the intrahepatic biliary tree. "In intrahepatic cholangiocarcinoma (ICC), UBE2T serves as an independent indicator of poor prognosis and a potential drug target for future molecular-targeted therapies." (PMID 39791716, 2024).
mesothelioma (1 paper, 2022). A usually malignant and aggressive neoplasm of the mesothelium which is often associated with exposure to asbestos. "For instance, the high UBE2T levels were associated with poor OS in ACC, BRCA, KIRC, KIRP, brain lower-grade glioma (LGG), LIHC, LUAD, mesothelioma (MESO), but associated with favorable OS in OV." (PMID 36357897, 2022).
myelodysplastic syndrome (1 paper, 2023). A clonal hematopoietic disorder characterized by dysplasia and ineffective hematopoiesis in one or more of the hematopoietic cell lines. "In summary, we demonstrated for the first time that the USP7, USP15, and UBE2T genes might be related to MDS pathogenesis and prognosis, supporting the importance of these genes in understanding the etiology and prognostic stratification of Myelodysplastic Syndrome." (PMID 37373211, 2023).
Pca (1 paper, 2022). "Recently studies found that the high expression level of UBE2T was related to tumour formation, invasion, metastasis and poor disease‐free survival of PCa patients." (PMID 36168930, 2022).
prostate tumors (1 paper, 2015). "Of note, we discovered a positive correlation between UBE2T and vimentin expression, both expression levels of UBE2T and vimentin are associated with the malignant properties of prostate tumors." (PMID 26308072, 2015). "In order to confirm whether the growth-promoting effect of UBE2T observed in cultured cells is relevant to prostate tumor growth in vivo, Du145 cells with ectopic or silent expression of UBE2T were subcutaneously inoculated into BALB/C athymic mice respectively." (PMID 26308072, 2015).
squamous cell neoplasm (1 paper, 2021). A neoplasm that is composed of squamous epithelial cells. "We extracted data on 10 normal tissues and 80 squamous cell neoplasms from the TCGA–ESCA projects and verified significantly enhanced UBE2T expression in ESCC." (PMID 34257599, 2021).
tumor (65 papers, 2003 to 2026). "In order to further verify that high expression of UBE2T is associated with poor prognosis and closely related to tumor development, we compared the expression levels of UBE2T in different groups of patients with different clinicopathological factors." (PMID 39367897, 2025). "High expression levels of UBE2T are associated with poor differentiation, advanced tumor classification (T classification), and an overall poor prognosis." (PMID 39791716, 2024). "By analyzing single-cell RNA sequencing data of Pan-cancer, we found that UBE2T was associated with the most fundamental tumor-associated cellular events, including cell cycle, DNA repair, EMT, proliferation, and stemness." (PMID 36357897, 2022). "Another enzyme, the Ubiquitin-conjugating enzyme E2T (UBE2T), is correlated with tumor recurrence, highly expressed in GBM, and associated with poor prognosis, EMT regulation, and invasion of GBM cells through GRP78." (PMID 35784465, 2022). "Consistently, compared with vehicle treatment, challenging tumor-bearing mice with Lef caused slower tumor growth and lighter tumor weight of the xenografts derived from UBE2T-overexpressing HCC cells." (PMID 35169125, 2022). "Statistical analysis by SPSS software revealed that higher expression of UBE2T was associated with larger tumor size (p = 0.023), venous invasion (p = 0.049), and advanced tumor stage (p = 0.045)." (PMID 33542213, 2021). "First, we found that overexpression of UBE2T at both the mRNA and protein levels was associated with advanced tumor stages and poor patient survival." (PMID 33542213, 2021). "We found high levels of CDC16 and UBE2T associated with tumor tissues with intestinal and diffuse GC, respectively." (PMID 33351778, 2020). "Next, we analyzed the association between UBE2T expression in tumor tissue and clinical pathological parameters of patients with NPC." (PMID 26943030, 2016). "Furthermore, UBE2T expression levels, influenced by the tumor microenvironment, correlate with immunoregulatory processes, including tumor-associated immune cell infiltration." (PMID 39791716, 2024). "By mediating the ubiquitin-proteasome pathway, UBE2T regulates the degradation and activity of target proteins, influencing several critical processes associated with tumor progression, including cell cycle regulation, signal transduction, and cancer cell stemness." (PMID 39791716, 2024). "Moreover, SENP1 knockout suppresses tumor development and progression while UBE2T overexpression or UBE2T K8R mutation in HCC cells displayed opposite impact." (PMID 31969492, 2020). "Notably, UBE2T has also been associated with immune evasion of LUAD tumor cells, which may become a focus of future studies." (PMID 39791716, 2024). "Immunohistochemical staining of tumour tissues corroborated these findings, showing diminished UBE2T and p‐ERK1/2 expression in xenografts from BA‐treated mice." (PMID 41486508, 2026). "Mechanistically, BA inhibited MAPK/ERK signalling, and pharmacological reactivation of ERK reversed BA‐induced suppression of UBE2T and tumour growth." (PMID 41486508, 2026). "There is a certain difference between the two, and the expression of UBE2T in tumor tissues is significantly increased (p= 8.1e-07)." (PMID 39367897, 2025). "UBE2T expression is upregulated in LUAD, and this upregulation is associated with tumor growth, lymph node metastasis, distant metastasis, and poor prognosis." (PMID 40650277, 2025). "The expression level of UBE2T is lower in normal tissues, while the lower the degree of tumor differentiation, the higher the expression level of UBE2T." (PMID 39367897, 2025). "Next, we evaluated the expression of UBE2T in 10 UCEC tumor tissues and 10 adjacent tissues by Western blot analysis." (PMID 39367897, 2025).